LOX (lysyl oxidase)
Diseases named in the same sentence as LOX in open-access papers (continued):
Sharing a sentence is not in itself a finding about the gene and the disease.
tumor (continued). "Reduction of macrophages through anti-CSF1 antibodies in the MMTV-PyMT mouse model led to reduced macrophages, diminished collagen deposition, reduced LOX expression and collagen crosslinks, and decreased lung metastasis, particularly when treatment occurred before the onset of tumor invasion." (PMID 37296891, 2023). "Moreover, aminomethylenethiophenes (AMTs) is a potent oral bioavailable anti-tumor agent targeting dual LOX and LOXL2 and exhibit improved pharmacokinetic properties and excellent antitumor efficacy in vivo." (PMID 36906534, 2023). "Moreover, the hypoxic microenvironment induces the synthesis of lysyl oxidase (LOX), which promotes the invasion and migration of tumour cells." (PMID 37753372, 2023). "Thus, LOX activities are silenced by the ATP7A gene to inhibit tumour growth and metastatic potential in cancer cell lines." (PMID 37049685, 2023). "Osteoclast-driven premetastatic lesion development in the bone may be mediated by extracellular matrix crosslinked by LOX activity, which is critical for the recruitment of pro-tumour immunological and stromal cells." (PMID 37375846, 2023). "Finally, it should be noted that while EVs are scrutinized for their role in the priming of premetastatic niches, tumor cells can also prime distal macrophages via their release of free enzymes such as lysyl oxidase (LOX)." (PMID 37429944, 2023). "Moreover, given the inability of LOX inhibition to consistently suppress primary tumor growth, future research should center on the development of LOX-based combination therapies that control the progression of both primary and metastatic lesions." (PMID 35804902, 2022). "The effects of LOX inhibition on subcutaneous xenograft tumor model were explored." (PMID 35966586, 2022). "Indeed, LOX functions as a promoter of angiogenesis, and was observed to enhance tumor angiogenesis in several types of cancer." (PMID 35682926, 2022). "The metastatic process is inhibited by a LOX inhibitor, suggesting that chemotherapeutic treatment enhances metastasis through the recruitment of LOX-expressing immune cells, which turn pre-metastatic niches, such as lungs, more receptive to colonization by metastatic tumor cells." (PMID 35682926, 2022). "Subsequent studies demonstrated that the anti-tumor activity of LOX-PP is through the direct or indirect inhibition of the Hsp70 and the suppresion of the MAPK/ERK pathway, Akt, FGFRs, RPTPĸ signaling, FAK, and others depending on the cellular or cancer context." (PMID 35563478, 2022). "It is similarly unclear if the shorter or longer produced LOX-PPs or short peptide fragment 159–167 would have different tumor modulating properties as might be expected from the apparent loss of tumor inhibitory properties of the Gln variant." (PMID 35563478, 2022). "In addition, the expressions of CD40L, CD40 and LOX increased with the tumour grade in all patients, and higher expressions of the target genes were observed in the mesenchymal type." (PMID 35908277, 2022). "Considering copper involvement in the functioning of the LOX protein which is responsible for cell migration, ATOX1 may facilitate the function of LOX enhancing tumor ability for metastasis." (PMID 36296659, 2022). "Finally, we investigated the association between LOX expression and the ESCA tumor immune microenvironment (TIME)." (PMID 36090891, 2022). "Firstly, DEGs were screened between normal and tumor tissues, and a hub gene LOX was identified." (PMID 36090891, 2022). "Because, high expression of CD40L, CD40 and LOX may reflect tumour malignancy in GBMLGG dataset, thus CD40L, CD40 and LOX expressions are associated with patient clinical outcomes." (PMID 35908277, 2022). "Collagen crosslinking by LOX increases tumor stiffening in mammary cancer tissues." (PMID 35205794, 2022).
tumor (continued). "Furthermore, low levels of methylation at some cg sites in the LOX gene were found to be strongly correlated with poor OS and PFS and methylation levels of LOX are negatively correlated with advanced tumor stage." (PMID 36202905, 2022). "D-pen has been found to inhibit LOX secretion and impair collagen cross-linking in tumor therapy." (PMID 36419894, 2022). "In addition, LOX secreted by CAFs can promote tumor proliferation by enhancing the Warburg effect mediated by the AKT/p70S6K/HIF1-α pathway in tumor cells." (PMID 36293126, 2022). "HIF-1α and LOX promote tumor development in coordination with each other." (PMID 36419894, 2022). "Similarly, inhibition of LOX expression resulted in reduced ECM stiffness in the mammary gland, preventing fibrosis and reduced tumour susceptibility." (PMID 35160252, 2022). "The results showed significantly elevated proteins levels such as thrombospondin-1 (TSP1), vascular endothelial growth factor (VEGF), and protein-lysine 6-oxidase (LOX), which have been well documented to be associated with tumor progression, angiogenesis, and treatment resistance." (PMID 35812406, 2022). "a major increase in lysyl oxidase activity was observed within the second and third weeks after treatment, which investigated LOX secretion by tumor cells which could promote treatment resistance." (PMID 35189882, 2022). "Meanwhile, tumor grade was significantly correlated with the expression of LOX and LOXL3." (PMID 35433829, 2022). "Furthermore, a close association between the expression of LOX and LOXL3 with tumor immune infiltration was verified, uncovering the potential molecular mechanism underlying the carcinogenesis in PDAC." (PMID 35433829, 2022). "Recent research found that LOX plays a critical role in tumor cell proliferation and survival." (PMID 36202905, 2022). "In addition, we found that methylation levels of LOX are negatively correlated with advanced tumor stage." (PMID 36202905, 2022). "Since the metastatic activity of LOX is strongly linked to its enzyme activity and fibrosis, one could propose that high levels of ADAMTS2 or 14 would act as fibrosis inhibitors or tumor suppressors." (PMID 35563478, 2022). "In addition, epigenetic activation of LOX via lncRNA/miR-29c has also been demonstrated to facilitate M2 macrophage polarization and tumor immune escape, finally rendering tumor cells resistant to chemotherapeutic drugs in gastric cancer." (PMID 36160460, 2022). "However, in such a situation, LOX has been described as pro-tumorigenic and pro-metastatic through its mature and active region, while the pro-region acts inversely as an anti-tumor factor." (PMID 35163744, 2022). "Results of this study, investigated effects of treatment with Vincristine on LOX secretion by tumor cells which could promote treatment resistance." (PMID 35189882, 2022). "Interestingly, while mature LOX was found to enhance tumor progression, LOX-PP was found to function as a tumor suppressor." (PMID 36232621, 2022). "Meanwhile, LOX is closely related to tumor cell proliferation, invasion, and metastasis." (PMID 34595188, 2021). "Additionally, the pro-peptide region of LOX, once cleaved from the mature LOX enzyme, has been shown to act as a tumour suppressor, whereas the mature enzyme is generally accepted to act as a tumour promoter." (PMID 33513979, 2021). "Thus, pharmacologic LOX inhibition results in disrupted collagen fibers, decreased estrogen receptor signaling activity, and decreased tumor cell proliferation and tumor progression." (PMID 33616307, 2021). "The colocalization of CAFs and LOX in tumor stroma were explored in OSCC tissues." (PMID 34930321, 2021). "Inhibition of LOX gene led to an improved response to chemotherapy in tumor models." (PMID 33828127, 2021). "In contrast, the tumour-suppressing activities of LOX are attributed to the released pro-peptide." (PMID 34095157, 2021).
tumor (continued). "Some studies also show that pro-metastatic function of LOXL-2 is independent of its role in ECM remodeling; others show that increased LOX secretion in the same tumor type increases matrix stiffening through collagen crosslinking, causing tumor cell dissemination and metastasis." (PMID 33639646, 2021). "In contrast, as tumor stiffness decreased by inhibition of LOX, T cell migration was restored." (PMID 34106045, 2021). "Inspired by this biochemical pathway, we demonstrate the reactive oxygen species (ROS) induced tumor therapy by integrating lactate oxidase (LOx) and catalase (CAT) into Fe3O4 nanoparticle/indocyanine green (ICG) co-loaded hybrid nanogels (designated as FIGs-LC)." (PMID 34475406, 2021). "Specific ECM tumor-targeting and intrinsic antitumor activity of LOX could enhance the efficacy of standard anthracycline-based regimens by directing accumulation to tumors." (PMID 33658580, 2021). "Blocking the activity of LOX in peripheral blood suppresses tumor cell seeding in lungs." (PMID 33258011, 2021). "In addition to LOX and MMPs, tumor-derived exosomes actively participate in the metastatic niche preparation." (PMID 34298680, 2021). "In addition, the hypoxic microenvironment results in lysyl oxidase (LOX) production, which increases tumor cells invasion and facilitates migration and metastasis." (PMID 35155571, 2021). "Therefore, we designed an anti-LOX engineered drug delivery system to efficiently target and concentrate anthracyclines within the tumor ECM." (PMID 33658580, 2021). "Tumour tissues tend to become stiffer as the tumour progresses, due to several factors, such as increased matrix deposition, cross-linking by lysyl oxidase (LOX) and TG2 enzymes, matrix remodelling, and the accumulation of both solid and interstitial pressures." (PMID 34205140, 2021). "In addition, using microarray analysis, we also identified the overexpression of LOX and PTX3 in KARS and PIK3CA mutant cell lines compared to the HMOsisEC10 cells, which was associated with the aggressive behavior of the benign tumor." (PMID 34202354, 2021). "The G473A polymorphism, causing an arginine (Arg) 158 to glutamine (Gln) substitution in a highly conserved region within Lysyl oxidase propeptide (LOX-PP), may reduce the ability of LOX PP to suppress the ras signaling and thus may increase the tumor risk." (PMID 35054220, 2021). "Moreover, we show the potential use of LS-AuNPs for the detection of LOX levels in tumor tissues isolated from mice tumor models and further examine the correlation between the LOX levels and the collagen content and the ECM stiffness in the tumor." (PMID 34572752, 2021). "Interestingly, it has been suggested that LOX displays a specific role in the late stage of metastasis more than in the growth of the primary tumor." (PMID 33946660, 2021). "The results above suggest that immune escape of cancer cells mediated by immune checkpoint may be an important prognostic factor of high LOX expression-mediated tumor progression." (PMID 35047494, 2021). "Previous studies have linked LOX-mediated collagen cross-linking and a stiffer ECM, which may promote the development of the pre-metastatic niche and tumor metastasis." (PMID 34426581, 2021). "Therefore, the LS-AuNPs developed in this study can be used to detect LOX levels and can be further used to predict the stiffness or the anticancer drug resistance of the tumor." (PMID 34572752, 2021). "However, recent studies found that LOX expression was significantly increased in tumor tissue and correlated with poor clinical outcomes of CRC patients." (PMID 33750326, 2021). "LOX can be a molecular target for improving the efficacy of chemotherapies against different types of solid tumors, as it has been reported to promote tumor progression by regulating collagen cross-linking." (PMID 34930321, 2021). "In addition, in xenograft glioma tumor mouse models, CBD induces tumor cell death by modulating the LOX/COX-2 pathway." (PMID 33921049, 2021).
tumor (continued). "The univariate and multivariate COX analyses indicated that LOX expression in tumor stroma could serve as an independent prognostic factor for the overall survival (OS) of OSCC patients." (PMID 34930321, 2021). "LOX inhibition increases the efficiency of anti-PD-1 therapy in KPC tumor model." (PMID 34106045, 2021). "Furthermore, IHC staining of tumor tissue sections against LOX revealed strong LOX expression in the MDA-MB-231 tumors and limited LOX expression in the MCF-7 tumors." (PMID 34572752, 2021). "However, a past study showed that LOX is a tumor suppressor gene that is inactivated due to methylation and loss of heterozygosity in GC and even other cancers." (PMID 34595188, 2021). "As for possible effects of LOX inhibition on tumor blood vessels, previous studies have reported reduced angiogenesis after LOX and LOX-like protein inhibition and an increased perfused vessel density in the case of overexpression of LOX." (PMID 34106045, 2021). "Thus, LOX plays an important role in tumorigenesis and in lowering the tumor response to anticancer drugs." (PMID 34572752, 2021). "We proved that a lipid-based nanocarrier targeting LOX and loaded with anthracycline is feasible and it could successfully provide significant therapeutic advantages (i.e. increased tumor growth inhibition and reduced toxicity)." (PMID 33658580, 2021). "The upregulation of LOX under hypoxic conditions is also involved in the recruitment of inflammatory stromal cells and bone marrow-derived cells at sites distant to the primary tumor, aiding the formation of the premetastatic niche." (PMID 33669630, 2021). "Based on this, we hypothesized that LOX-dependent tumor stiffness could consequently affect T cell migration in tumors and eventually predict the T cell behavior in the various ECM environments." (PMID 34106045, 2021). "Together, the sensitive determination of LOX levels in tumors may enable the prediction of the stiffness of tumor ECM and thereby may provide more accurate and precise ways to enhance anticancer effectiveness in patients with cancer." (PMID 34572752, 2021). "Importantly, LOX is recognized as a core factor of the hypoxic tumor microenvironment, such as through forming a feedback loop with HIF-1α." (PMID 34583752, 2021). "Moreover, the high expression of LOX in tumor stroma was observed in the same regions of the high expression of α-SMA and FAP." (PMID 34930321, 2021). "Indeed, some LOX members (in particular LOXL2) promote tumour cell survival, regulate cell adhesion, motility and invasion, and remodel the TME." (PMID 33544155, 2021). "LOX overexpression may affect the tumor microenvironment, tumor desmoplasia (fibrosis), and also stimulate anchorage-independent growth of OSCC cells." (PMID 33143101, 2020). "Interestingly, LOX-PP processed from pro-LOX protein appears to play a tumor-suppressive role on HCC cells." (PMID 33371259, 2020). "Moreover, the interplay between tumor cells and stroma (epithelial, endothelial and immune cells) is critically involved in tumor progression from the LOX perspective." (PMID 32184727, 2020). "LOX promotes tumor cell migration and adhesion by activating the focal adhesion kinase (FAK1)." (PMID 33271772, 2020). "It has been proposed that LOX may reduce drug penetration under hypoxic conditions and lessen the cytotoxicity of chemo-agents in 3D collagen cultured cells and tumor models." (PMID 32415208, 2020). "NDGA decreases tumor progression in various preclinical models by inhibiting metabolic enzymes that are critically involved in prostate, lung, esophageal and skin cancers (e.g. fatty acid synthase and LOX enzymes)." (PMID 32184727, 2020). "Since LOXL1 is highly homologous to LOX, we hypothesized that its tumour suppressor activity is also dependent on its intracellular function." (PMID 32912229, 2020). "LOX expression is increased in tumor cells through hypoxia-inducible factor-1 (HIF-1) stimulation." (PMID 32537166, 2020).
tumor (continued). "The presence of hypoxia in the tumor environment can generate CSCs and cause acquisition of radiotherapy-resistance, and under hypoxic conditions, HIF-1α and LOX are stabilized and secreted, respectively, and mediate premetastatic niche formation to promote cancer metastasis." (PMID 33126606, 2020). "It has been shown that LOX-dependent crosslinking of collagen fibers is involved in creating a “growth-permissive fibrotic microenvironment” for metastatic growth and the opportunity of tumor cell persistence." (PMID 32537166, 2020). "By using immunohistochemistry, we found co-occurrence of stromal CAFs and senescent TC cells at the tumor invasive front, where deposition of collagen (COL1A1) and expression of lysyl oxidase (LOX) enzyme were also detected, in association with features of local invasion." (PMID 31906302, 2020). "Similar involvement of LOX in tumour dissemination was reported for undifferentiated pleomorphic sarcoma (UPS), where HIF1 alpha promoted the expression of PLOD2, and PLOD2 inhibition led to a decrease in collagen deposition, organisation and maturation, and a decrease in lung metastases." (PMID 33066583, 2020). "Furthermore, the tumor-suppressive effects of LOX on RAS-mediated transformation are mediated by the RAF-heat shock protein 70 (HSP70) axis, which is also linked to NF-κB." (PMID 32424143, 2020). "Additionally, we examined how weekly infusion of a 20% top-load dose of PolyhHb influences growth rate, vascularization, and regional blood flow in the FME and LOX tumor xenografts." (PMID 32647211, 2020). "LOX proteins may play complex and paradoxical roles in the metastatic process or may act as tumor suppressors." (PMID 33271772, 2020). "Inhibition of LOX and biglycan reduces tumor metastasis suggesting the relevance of LOX targeting." (PMID 32775327, 2020). "Furthermore, cross-linking and collagen bundling, regulated by the cross-linking enzymatic activity of LOX, create the molecular tracks that pave the way for cancer cells to migrate beyond the primary tumor." (PMID 32604738, 2020). "Before tumor formation, LOX inhibitors showed strong tumor-inhibiting capacity." (PMID 31106200, 2019). "However, during cancer progression ECM protein deposition is increased alongside with increased levels of LOX protein resulting in a stiffer tumor ECM." (PMID 31130685, 2019). "Therefore, LOX likely contributes to the stabilization of cell surface integrins resulting in tumor progression." (PMID 31130685, 2019). "Indeed, silencing of ATP7A was able to inhibit LOX activity and, as a result, to suppress LOX-dependent mechanisms of tumor progression." (PMID 31540259, 2019). "Matrix stiffness driven by LOX is indeed required for hypoxia-induced tumor metastasis." (PMID 31861892, 2019). "Cu-dependent enzymes whose role in tumor growth and/or metastasis has been documented comprise mitogen-activated kinase 1, superoxide dismutase 1, cytochrome c oxidase, and the lysyl oxidase (LOX) group of proteins." (PMID 31540259, 2019). "However, we also noted distinct staining patterns in the tissues, particularly extensive TG2 expression in tumour stroma, and LOX expression that was prominent in the epithelia, indicating distinct regulation of the two enzymes in vivo." (PMID 31117256, 2019). "While radiotherapy increases LOX secretion in several tumor cell types and in in vivo lung adenocarcinoma xenograft models, knockdown of LOX2 in DU145 prostate cancer cells using a siRNA approach enhanced their radiosensitivity not only in vitro but also in a xenograft model." (PMID 32118030, 2019). "In addition, an orthotopic implantation metastasis model also confirmed that the EGFR inhibitor WZ4002 and silibinin decreased tumor metastasis through the EGFR/LOX pathway." (PMID 29472856, 2018). "As previously reported, LOX may be an important regulator in cancer cells migration, invasion and the formation of a mature extracellular matrix which promotes tumor progression." (PMID 29472856, 2018).